INS (insulin)
Diseases named in the same sentence as INS in open-access papers (continued):
Sharing a sentence is not in itself a finding about the gene and the disease.
Hyperglycemia (continued). "Short-term hyperglycemia by insulin discontinuation is associated with an increase in myocardial systolic contractile function in type 2 diabetic patients with and without heart failure and with a slightly prolonged walking distance in type 2 diabetic heart failure patients." (PMID 23308171, 2013). "Inflammation caused by cytokines such as IL6 and TNFα in response to TB infection may cause an increase in insulin resistance and decreased insulin production, thereby leading to hyperglycemia." (PMID 24360398, 2013). "However, xylazine-induced hyperglycemia in rats, sheep, cattle, and dogs is associated with a reduction of insulin secretion, while a significant rise in plasma insulin levels occurs in horses." (PMID 24138083, 2013). "Both pathogenic states induce hyperglycemia and therefore increase insulin demand." (PMID 23542897, 2013). "Importantly, the marked hyperglycemia that occurred in the CLP Glu group was associated with plasma insulin levels similar to the Sham Glu group, which exhibited blood glucose levels 2-3 times lower than the CLP Glu group (219±13 mg/dL, p=0.002)." (PMID 23826335, 2013). "Rictor/mTORC2 also was found to be important for maintaining β-cell proliferation and cell size, since Rictor null mice exhibited mild hyperglycemia and glucose intolerance caused by a decreased β-cell mass, β-cell proliferation, pancreatic insulin content, and glucose-stimulated insulin secretion." (PMID 22680924, 2012). "Hyperglycemia is associated with glucose intolerance and tissue resistance to insulin." (PMID 22257465, 2012). "It has been proposed that in AMI patients, decreased levels of blood insulin associated with hyperglycemia may lead to a decrease of glycolytic substrate for cardiac muscle." (PMID 22830071, 2012). "High or frequent intakes may particularly cause hyperglycemia in subjects with reduced insulin sensitivity, such as during pregnancy." (PMID 23095173, 2012). "By comparison, the roles of CREB in insulin producing β-cells are relatively unknown except that inhibition of CREB in transgenic mice with a dominant negative A-CREB causes severe hyperglycemia due to the loss of β-cell mass." (PMID 22509362, 2012). "A study that targeted hyperglycemia and oxidative stress with insulin and antioxidants (vitamin E and C), respectively in diabetic rats found that the combination of these two classes of agents normalized hyperglycemia, weight loss and oxidative stress parameters more considerably than either agent." (PMID 22489136, 2012). "It is interesting to note that use of continuous insulin infusion in the intensive care setting in order to rapidly correct hyperglycemia has been associated with improved survival, which may be due in part to the elevated risk of bacteremia in hyperglycemia." (PMID 22390383, 2012). "These colonies maintained insulin expression for at least 2 weeks after transplantation into vascularised chambers of immune deficient, hyperglycaemic mice, but persistent hyperglycaemia necessitated euthanasia of the mice." (PMID 23152835, 2012). "Hyperglycemia, other metabolic disorders, and chronic complications due to an absolute lack of insulin and/or a reduction of the biological effects of insulin may cause the appearance of corresponding sugars in urinary metabolites." (PMID 22778781, 2012). "Heterozygous mutations in the human GK-encoding GCK gene that reduce the activity index increase the glucose-stimulated insulin secretion threshold and cause familial, mild fasting hyperglycaemia, also known as Maturity Onset Diabetes of the Young type 2 (MODY2)." (PMID 22291974, 2012). "The exocrine and endocrine pancreases develop normally in Perk-/- mice, but there is a progressive loss of insulin-producing pancreatic beta cells in the islets of Langerhans of Perk-/- mice postnatally, resulting in hyperglycemia and reduced serum insulin levels." (PMID 22474424, 2012).
Hyperglycemia (continued). "Studies on streptozotocin-induced diabetic rats have shown that NS may reduce hyperglycaemia, increase serum insulin concentrations, and promote partial regeneration or proliferation of pancreatic beta cells, causing an increase in insulin secretion." (PMID 22973403, 2012). "As this condition goes on, further damage of pancreatic cells, as a result of severe hyperglycemia, is liable to cause defective insulin secretion and could be the starting point for initiation of glucose tolerance disturbances." (PMID 23227034, 2012). "Further improvements in reducing the pharmacological variability of rapid- and long-acting insulin would be expected to lower the risk of hypoglycaemia and hyperglycaemia, as well as simplify and perhaps also encourage, optimal insulin titration in real-life clinical practice." (PMID 21410860, 2011). "Hyperglycemia was associated with elevated insulin levels in half of the children." (PMID 21276273, 2011). "Persistently increased glucose and insulin levels as shown in this study are of serious clinical concern since hyperglycemia has been frequently linked to impaired wound healing, increased skin graft loss, increased muscle protein catabolism, increased incidence of infections and mortality." (PMID 21789167, 2011). "We hypothesized that the combined metformin and diazoxide therapy would lower insulin secretion while minimizing the risk of hyperglycemia, leading to weight loss and improvement in metabolic status." (PMID 21603206, 2011). "Homozygous pdx1 inactivation during embryogenesis results in early onset diabetes due to decreased beta cell mass and increased alpha cell area at birth while a heterozygous inactivation results in persistent hyperglycemia with a relative deficiency of plasma insulin." (PMID 21765202, 2011). "The expression pattern of these genes is consistent with the metabolic memory phenotype and demonstrates that even a one month period of loss of insulin signalling and hyperglycemia can result in molecular alterations that are unresponsive to insulin treatment." (PMID 21575160, 2011). "Thus, loss of local insulin signaling and systemic hyperglycemia have both common and separable effects on the retina." (PMID 22046295, 2011). "Chronic hyperglycemia may lead to serious damage to many organs and cause the impairment of insulin production and action." (PMID 21113299, 2010). "Common variants of MTNR1B, G6PC2 and GCK are associated with elevated FPG and impaired insulin secretion, both individually and jointly, suggesting that these risk alleles may precipitate or perpetuate hyperglycemia in predisposed individuals." (PMID 20628598, 2010). "Hyperglycemia has long been known to cause insulin desensitization." (PMID 20851344, 2010). "• Hyperglycemia is common in critically ill patients, is associated with increased morbidity and mortality, and strict glycemic control with insulin may improve outcomes in some populations." (PMID 20128893, 2010). "PH exposure in utero may cause withdrawal symptoms, but it generally induces hyperglycemia by inhibiting the release of insulin as a result of the blockage of calcium uptake via voltage−dependent calcium channels." (PMID 21274347, 2010). "It is important that patients adjust their insulin doses appropriately in response to factors such as carbohydrate intake, lifestyle, exercise and intercurrent illness to minimise the risk of hypo- or hyperglycaemia." (PMID 20456170, 2010). "As hyperglycemia is associated with increased mortality in critically ill patients and worsens the outcome in severely burned patients, we determined serum insulin levels in our four burn groups." (PMID 17716366, 2007). "Moreover, disturbances in insulin signaling and hyperglycemia are associated with hippocampal dysfunction, which may directly weaken verbal learning capacity." (PMID 41601482, 2026).
Hyperglycemia (continued). "Interestingly, rats induced with diabetes by streptozotocin (STZ) and untreated with insulin show similar alterations seen in humans, such as hyperglycemia, polydipsia, polyuria, and weight loss, as well as cardiomyopathy, diabetic neuropathy, and increased oxidative stress." (PMID 40143095, 2025). "Moreover, evidence suggests that dietary carotenoids may not only reduce oxidative stress associated with hyperglycemia but also improve insulin signaling pathways." (PMID 40563357, 2025). "In patients with T2D, prolonged disease duration may lead to a gradual decline in insulin production and function, and long-term insulin deficiency can lead to chronic hyperglycaemia and decreased bone turnover, affecting osteoclast activity and promoting bone resorption." (PMID 40566336, 2025). "Furthermore, insulin-based therapies are being explored for their ability to facilitate corneal wound healing and metabolic regulation, potentially serving to reverse the impairments caused by hyperglycaemia." (PMID 39797325, 2025). "However, timely diagnosis is critical to minimize exposure to hyperglycemia and reduce the risk for complications, as individuals with T1D rely entirely on exogenous insulin and require intensive self-management to prevent acute complications like hypoglycemia and ketoacidosis." (PMID 41361045, 2025). "In addition, hyperglycemia has been associated with vascular ischemia, accumulation of amyloid β, and impaired insulin signaling in the brain changes that may contribute to Alzheimer's-like neuropathology." (PMID 40792127, 2025). "Therefore, we speculate that in malaria, galactin-3 may associate with worsening hyperglycaemia through impaired insulin release in diabetics but heightens beta-cell secretory function in non-diabetic respondents." (PMID 40802820, 2025). "Human factors such as prioritizing hyperglycaemia avoidance, normalizing asymptomatic hypoglycaemia and minimizing hypoglycaemia concerns have been demonstrated to increase the risk of SH by driving self‐management decisions including excess or early insulin bolusing and insulin stacking." (PMID 39996361, 2025). "These improvements included changes in blood insulin levels, HbA1c, blood glucose, hepatic glucose-regulating enzymes, and pancreas weight, suggesting that it may effectively control hyperglycemia symptoms caused by the loss of pancreatic islet β-cell function." (PMID 40002361, 2025). "Its etiology of hyperglycemia can be distilled to insulin resistance (i.e., progressive impairments in insulin sensitivity) and islet failure (i.e., insulin relative hyposecretion of pancreatic islets lead to a loss of compensation for the decline in insulin sensitivity)." (PMID 39710722, 2024). "It appears that the activity of insulin hinders the synthesis of glycogen in the liver, and at the same time, the gluconeogenesis pathway affects the concentration of blood sugar in many respects, eventually causing metabolic diseases such as hyperglycemia and hyperlipidemia." (PMID 39272556, 2024). "One case report linked hyperglycemia to psychotic symptoms, and a case series showed that poor blood glucose management may have been connected to psychosis, particularly as increased insulin is associated with mood alteration." (PMID 38414502, 2024). "Consequently, the lower insulin requirement in the 150 mg/kg group may result in fewer side effects associated with hyperglycemia." (PMID 39070316, 2024). "Since higher cutoff can result in underestimation of β-cell function and may lead to unnecessary insulin treatment, while lower cutoff can overestimate β-cell function and impose the patients to the risk of hyperglycemia complications by unsuccessful transition to non-insulin therapy." (PMID 39252700, 2024). "However, hyperglycaemia causes podocytes to become insulin resistant." (PMID 39456664, 2024).
Hyperglycemia (continued). "However, a few precautions need to be taken for this population because high insulin levels during and after exercise can cause hypoglycemia, and low insulin levels may result in hyperglycemia and ketosis [97?]." (PMID 39616333, 2024). "Thus, maternal obesity can create a multi-faceted shift in nutritional metabolic balance, adipokine and cytokine presence which impairs the adaptive response of the maternal pancreas to increase BCM and insulin release, increasing the risk of maternal hyperglycemia, GDM, and fetal overgrowth." (PMID 39377073, 2024). "Additionally, sometimes overcorrection of hyperglycemia occurs after PA, via repeated insulin dose administration, resulting in an increased risk of severe late-onset hypoglycemia, which could even be fatal." (PMID 38542818, 2024). "The ability of LSB to significantly lower hyperglycemia, improve body weight gain and glucose tolerance may be linked to its insulin secretory ability as suggested by the increased insulin levels, as well as increased mass and number of β-cells in the pancreas of the treated animals." (PMID 39070783, 2024). "Incorporating DHA into the diet of an obese individual may have the potential of restoring balance and reverse the dysregulation of the ECS, resulting in an increase of glucose uptake into skeletal muscle and a reduction in insulin resistant-associated hyperglycemia." (PMID 37375583, 2023). "Similarly, the use of SC long-acting insulin was associated with a higher median number of hyperglycaemias per patient (2.5 vs 2; median difference: 2.5 [95%CI 2; 4]; P < 0.0001) and with higher counts of hyperglycaemia (IRR: 3.58 [2.84; 4.52]; P < 0.0001)." (PMID 37330419, 2023). "The prolonged exposure of human cells and tissues to hyperglycemia, on the other hand, promotes the accumulation of advanced glycosylation end-products in skeletal muscle, causing increased OS, mitochondrial dysfunction, and loss of the anabolic action of insulin." (PMID 37513585, 2023). "As a matter of fact, even though modern insulin analogs have a low immunogenicity, insulin antibodies may sometimes be detected in patients receiving insulin therapy, but these antibodies are rarely capable of causing hyperglycemia or hypoglycemia." (PMID 36844104, 2023). "Moreover, an increase in insulin production caused by hyperglycemia may increase the endogen production of AA, as insulin influences the rate limiting enzymes responsible for the conversion of LA to AA, thereby promoting an inflammatory effect." (PMID 36904164, 2023). "Although infection-induced inflammation and cytokine activation leading to insulin resistance may cause stress hyperglycaemia, it is unknown to what extent the direct destruction of islet cells by the virus, resulting in decreased insulin production and release, contributes." (PMID 37511334, 2023). "Furthermore, long-term exposure to hyperglycemia, which causes oxidative stress and inflammation, may alter gene expression regulation, resulting in lessened insulin production and the increased apoptosis of β-cells." (PMID 38004306, 2023). "Interestingly, this was the case even though the COVID-19-positive group required higher total prednisone-equivalent steroid doses to control the “cytokine storm”, which would usually require greater insulin requirements to control the hyperglycemia caused by steroids." (PMID 36741601, 2023).
Hyperglycemia (continued). "One molecular mechanism of action through which chronic hyperglycemia can cause worsening β‐cell function is via decreased protein expression of Pdx1, whereas the positive effects of glucose on insulin transcription may be a result of its enhancement of Pdx1 nuclear translocation." (PMID 37568265, 2023). "Insulin and leptin resistance and elevated levels of ghrelin, mediated by short sleep duration, have been associated with sleep restrictions and increased catecholamine and cortisol levels, and hypoxia can amplify hyperglycemia, negatively affecting these processes." (PMID 37366660, 2023). "We have previously reported that parenteral amino acid intakes reduce the risk of both hyperglycaemia and insulin treatment, and this may in part account for the similar mean blood glucose profiles and frequency of insulin treatment seen for the SCAMP and control infants." (PMID 38004135, 2023). "Data supported our hypothesis and demonstrated that 4 days following STZ administration, 35 mg/kg-treated mice secreted significantly more insulin than 55 mg/kg-treated mice and, therefore, were able to better manage hyperglycemia despite having similar levels of beta cell mass loss." (PMID 37458461, 2023). "As a chronic disease, DM is a metabolic disorder in which insulin production by the pancreas is reduced or the produced insulin may be ineffective, leading to hyperglycemia, which can cause further damage to other body systems like the circulatory and nervous systems." (PMID 37896054, 2023). "Possible mechanisms for this include neuropathic and inflammatory mechanisms, lower activity of anabolic hormones, as well as resistance to insulin by skeletal muscles, and hyperglycemia, which may accelerate muscle loss and sarcopenia, and in turn, physical function." (PMID 36650566, 2023). "Exactly how the loss of MAP3K15 may influence insulin signaling and hyperglycemia is still unclear." (PMID 36383675, 2022). "Therefore, relative dysfunction of pancreatic islet insulin secretion caused by the virus infection maybe the main reason of severe hyperglycemia in patients with COVID-19." (PMID 35673632, 2022). "This low pH associated with hyperglycemia induces steric deshielding of peptides on inner small liposomal vesicles (ISVs) containing pre-formed and stored insulin, and these peptides form coiled-coil structures with peptides on outer large vesicles (OLVs), leading to release insulin from the ISVs." (PMID 34586617, 2022). "Hyperglycaemia is caused by the inability of the body’s cells to fully respond to insulin, a phenomenon known as insulin resistance, which causes an overproduction of insulin as a compensatory mechanism, resulting in the failure of pancreatic beta cells and a dysfunction in insulin production." (PMID 35741413, 2022). "The reported increase in NPY/AgRP neuronal number is rescued by the normalisation of maternal hyperglycaemia following maternal pancreatic islet transplantation, demonstrating that the effect on the offspring’s hypothalamic morphology is caused by the change in maternal insulin or glucose levels." (PMID 35258482, 2022). "Treatment of hyperglycemia in hospitalized patients mainly consists of insulin administration; however, some reports have associated the previous use of insulin with higher mortality risk in patients with T2D, which could be mostly related to disease severity and other comorbidities." (PMID 35017617, 2022). "The leading causes of hyperglycemia are dietary carbohydrates’ digestion and absorption, glycogen storage reduction, β-cell dysfunction, peripheral tissue insulin resistance, deficiency in insulin signaling pathways, and improved gluconeogenesis and production of hepatic glucose." (PMID 36557912, 2022).